TF (transferrin)
Diseases named in the same sentence as TF in open-access papers (continued):
Sharing a sentence is not in itself a finding about the gene and the disease.
infection (continued). "Participant 079, who was ART-naive throughout the duration of the study, also exhibited viral diversification over time, with the TF variants clustering independently of the variants in the plasma, PBMC, and LN at chronic stage of infection." (PMID 36453881, 2022). "Among the six participants (036, 093, 102, 186, 208, and 318) who initiated ART at the chronic stage of infection, variants that were circulating in plasma before ART initiation clustered independently of the TF variants." (PMID 36453881, 2022). "After pathogen infection, the expression of these TF genes is repressed and the recruitment of HDAC is blocked leading to increased histone acetylation and gene activation." (PMID 36407628, 2022). "Despite the sequence and functionality of transferrin being preserved across different animals, the expression of transferrin in response to stress and infection varies in different species and its contribution to host defense is diverse and complex." (PMID 33600478, 2021). "We found that non-TF genes show few alterations in the GRNs that represent macrophages in the first hours after infection, as indicated by F1 metric calculated by LoTo for the presence or absence of network motifs in each compared GRN between 0.96 and 0.98." (PMID 34668739, 2021). "For example, there have been reports of TF prevalence >5% in communities with zero or near-zero prevalence of infection." (PMID 33861754, 2021). "We used photographic images, as well as a test of infection, to corroborate the field grading of TF." (PMID 33861754, 2021). "The aim of this study was to evaluate the expression of proteins in the TF of domestic cats before and after infection with Toxoplasma gondii, in the phases of acute infection and chronicity." (PMID 34906132, 2021). "In the human body, iron is sequestered by hemoglobin, hepcidin, lactoferrin, transferrin, etc., and during infection, it is actively restricted even further as a defense mechanism of the innate immune system." (PMID 34203370, 2021). "The percent of TF-positive children with infection (21.5%) was slightly less than that reported in another study of Kongwa District but still indicated the presence of infection in cases of TF." (PMID 33861754, 2021). "Mean log(MFI-BG) increased with age (p = <0.0001), as well as with presence of TF (p = 0.0003) and infection (p = <0.0001)." (PMID 33861754, 2021). "We found a TF prevalence of 7.1%, and 21.5% of TF-positive children tested positive for infection (p = <0.0001)." (PMID 33861754, 2021). "Overall, 90 TF genes comprising 24 families in PlantTFDB 5.0 and CBP60s were upregulated after infection and 22 WRKYs, 14 NACs, 5 CBP60s, and 5 HSFs were significantly (p-value < 0.05, hypergeometric distribution test) over-represented." (PMID 34666675, 2021). "These survey tools included prevalence of TF as determined by field grading and by grading of photographs taken of the children’s upper tarsal conjunctivae, testing for infection, and testing for antibody positivity to C. trachomatis antigen pgp3." (PMID 33861754, 2021). "A second limitation of the current study was that serological data were missing from 19% of children and infection data were missing from 12% of children with TF." (PMID 31965155, 2021). "While insect transferrin shares considerable sequence homology with mammalian serum transferrin, the exact mechanisms by which the expression of transferrin is activated upon pathogen infection are unclear." (PMID 33600478, 2021). "This can be a key factor in influencing the spread of infection in the body, because iron content in the body is limited during infections due to sequestration by host proteins such as lactoferrin, transferrin, and haemoglobin." (PMID 34683403, 2021). "In Fth1−/− mice, the decrease in transferrin saturation and serum iron upon infection were less pronounced." (PMID 35008695, 2021).
infection (continued). "Studies of high-TF villages in the Solomon Islands have shown infection prevalence, anti-Pgp3 antibody prevalence and scarring severity to be low despite high TF prevalence." (PMID 32017971, 2020). "Saturation of Hp and hemopexin by Hb and heme, respectively, has been reported to be more dangerous for the development of infections than transferrin saturation." (PMID 32245010, 2020). "For this purpose, we used transgenic mice expressing human transferrin as an experimental model that allows meningococcal growth by providing a human iron source during infection." (PMID 32022687, 2020). "During natural infection, C. burnetii likely encounters iron-containing molecules, including ferritin, hemoglobin, and transferrin." (PMID 32699121, 2020). "To distinguish which routes were involved in PRRSV infection mediated by TIM-1, we performed confocal microscopy in combination with transferrin or dextran during early infection (i.e., at 30 min postinfection [mpi]) in MARC-145 cells." (PMID 32522856, 2020). "We identified 119 TF genes that are differentially expressed upon spider-mite herbivory and we compared expression profiles of these TF genes with the expression profiles that were reported upon infection with an oomycete pathogen." (PMID 32796676, 2020). "Here, the measurement of three markers (ocular Ct infection, anti-Pgp3 antibodies and conjunctival scarring) was integrated with estimation of population-based prevalence of TF." (PMID 32017971, 2020). "During infection, the host iron is bound to proteins such as transferrin, ferritin, and haemoglobin." (PMID 33143139, 2020). "At different infection sites, free iron is sequestered within iron-binding proteins such as transferrin and lactoferrin." (PMID 33057423, 2020). "Under infection conditions, the concentration of free iron in body fluids is so low that transferrin saturation drops to 5%." (PMID 32245010, 2020). "Since transferrin is an acute-phase protein, the observed drop in transferrin saturation during infection results from a combination of increased plasma concentration of the protein and decreased iron absorption." (PMID 32245010, 2020). "Here, we focus on the regulation of the expression of TF genes by spider-mite herbivory and include a comparison with the response upon infection with a pathogen." (PMID 32796676, 2020). "A contig (CL847) homologous to insect transferrin was identified in the P. xylostella immunotranscriptome against infection by I. cicadae." (PMID 32380643, 2020). "Several human factors are involved in the development of invasive infections such as transferrin, factor H or CEACAM1." (PMID 32977487, 2020). "In contrast, the relationship between ocular Ct infection and TF in Vanuatu resembles findings from neighbouring Solomon Islands and Papua New Guinea, with the ocular Ct infection prevalence being considerably lower than the prevalence of TF." (PMID 32017971, 2020). "Increases in TF have been suggested to function by sequestering iron from bacterial utilization and thereby limiting infection." (PMID 31848364, 2019). "Infection of Aedes aegypti with Wuchereria bancrofti filarial nematodes has been shown to increase mRNA levels of defensin, cecropin and transferrin." (PMID 30813894, 2019). "Infection was induced by intramuscular inoculation, and subsequent imaging with [68Ga]apo-transferrin showed focal time-dependent uptake at the site of infection." (PMID 30736324, 2019). "Instead, it utilizes an arsenal of TonB-dependent transporters that bind directly to host nutritional immunity factors including transferrin, lactoferrin, and hemoglobin and strip them of their iron cargo, effectively co-opting them for support of infection." (PMID 31369630, 2019). "Upon infection with S. Typhimurium, transferrin saturation declined significantly, and DA treatment led to a further decrease in transferrin saturation." (PMID 30723125, 2019).
infection (continued). "On the other hand, it has been reported that iron starvation at the infection site in humans is due to the production of the iron-binding proteins, such as transferrin and lactoferrin." (PMID 31262762, 2019). "Since the sign of TF can persist long after infection clears, it is possible that degradation of Chlamydial DNA in the environment precluded finding even more positive environmental samples." (PMID 31869324, 2019). "Transferrin saturation presented as a significant predictive factor for infection occurrence when above 32.1% (median)." (PMID 31261772, 2019). "At high levels of infection and transmission PCR and TF prevalence correlate with one another due to rapid rates of reinfection occurring, ensuring that PCR and TF prevalence correlate well with one another." (PMID 30307939, 2018). "At baseline, the TF prevalence in all children in the baseline survey was 5.2% and the prevalence of infection was 4.9%." (PMID 29476106, 2018). "Considering the gene families, five out of 10 bHLH TF genes were differentially expressed in response to B. elliptica infection, and were up-regulated in the early stages (0 h, 1 d) of infection." (PMID 29443955, 2018). "The overall mean cluster-summarised TF prevalence (the clinical indicator) was 0.8% (95% CI: 0.6–1.0) and Ct infection prevalence was 0.04% (95%CI: 0.00–0.12)." (PMID 30550537, 2018). "Following a single round of treatment, the prevalence of PCR detectable infection dropped much more quickly than the prevalence of TF." (PMID 30307939, 2018). "This drastic gene expression change was mediated by expressional alteration of various known and novel Mtb-infection related TF genes including both M1 and M2 activation." (PMID 29712924, 2018). "The variance in the estimated PCR and TF prevalences were slightly higher for PCR detectable infection, whilst the variance in the estimated prevalence of TF and PCR overlapped at some sampling time points, this was not consistent for all sampling points." (PMID 30307939, 2018). "Although, B. pseudomallei can acquire the metal from transferrin via malleobactin, expression of TfR1 was unchanged following infection." (PMID 29329289, 2018). "Here, higher treatment efficacy resulted in faster infection rebound, leading to a higher final TF prevalence." (PMID 28182664, 2017). "Other studies have also shown transferrin upregulation in mosquito host response to pathogen infection, particularly Wuchereria bancrofti, in Ae. aegypti and C. quinquefasciatus females." (PMID 29387018, 2017). "Infection with the Lp01 ΔankX mutant showed a sharp decrease in accumulation of transferrin-positive vesicles, indicating that AnkX is largely responsible for disruption of endocytic recycling." (PMID 28944216, 2017). "Third, we report that during infection of macrophages, AnkX is responsible for the disruption of endocytic recycling of transferrin, and AnkX's phosphocholination activity is critical for this function." (PMID 28944216, 2017). "Final TF prevalence was 14% instead of 4% when the minimum duration of infection was decreased from 10 weeks to 5 weeks." (PMID 28182664, 2017). "In contrast, a 50% reduction in the minimum duration of infection resulted in fast infection re-bound resulting in a high final TF prevalence above the baseline results, until a 50% reduction in transmission was implemented." (PMID 28182664, 2017). "We also observed decreased expression of transcripts associated with immunity, including lectins, hemolectin (Hml) and transferrin upon infection, suggesting a reduction of tsetse defense systems." (PMID 29155830, 2017). "With the improved availability of commercial 68Ge/68Ga generators, other potential 68Ga-labeled radiopharmaceuticals were considered as infection imaging agents, such as 68Ga-citrate, 68Ga-apo-transferrin and 68Ga-siderophores." (PMID 28837117, 2017). "In Mastotermes darwiniensis, transferrin gene expression increases following infection with M. anisopliae." (PMID 28410430, 2017).
infection (continued). "Our data showed that, indeed, endocytic recycling of transferrin, a widely used marker for this transport pathway, is blocked early during macrophage infection." (PMID 28944216, 2017). "If the maximum rate of recovery from infection was changed to 0.008 from 0.006 final TF prevalence was 40%, in comparison to 2%." (PMID 28182664, 2017). "At 1 h post-infection, macrophages were subjected to a pulse-chase sequence with fluorescently labeled transferrin followed by incubation with unlabeled transferrin." (PMID 28944216, 2017). "Final TF prevalence for Model 2 when transmission was reduced by 10%, was 60% when the minimum duration of infection was 5 weeks, but 8% for the 10 week baseline value." (PMID 28182664, 2017). "In some settings TF prevalence persists at high levels despite relatively little infection being detected." (PMID 27783678, 2016). "Five of the 51 RIN > 8 samples with the highest RNA concentration that had TF with current Ct infection were chosen for sequencing." (PMID 26842862, 2016). "During invasive infection, meningococcal growth requires iron sources such as the human transferrin (hTf) and carbon sources." (PMID 27655040, 2016). "Below the 10% TF level the prevalence of infection was consistently low, and therefore below this level, TF prevalence appears to be a good marker for infection having being brought under control." (PMID 27783678, 2016). "Transferrin has also been shown to localize within the VAC during infection and its recycling has been shown to be suppressed by CMV microRNAs targeting host secretory factors." (PMID 27218650, 2016). "We explored the role of HPr using bioluminescent wild-type and ΔptsH strains in experimental infection in transgenic mice expressing the human transferrin." (PMID 27655040, 2016). "In this work we explored the role of HPr during infection using transgenic mice expressing the human transferrin that allows meningococcal growth by providing both iron and carbon sources." (PMID 27655040, 2016). "In this systematic review, we found that prior to the introduction of antibiotic treatment the relationship between the community-level prevalence of TF in children correlated well with that of infection." (PMID 27783678, 2016). "Lower levels of transferrin after the initiation of inflammation due to infection, tissue injury, trauma, or immunological disorders lead to low levels of serum iron, which prevents microbial growth and is therefore beneficial for the infected organism." (PMID 27090083, 2016). "We identified a reasonable number of studies reporting the community-level relationship between disease and infection prior to treatment, over a wide TF prevalence range." (PMID 27783678, 2016). "They suggested that TF data alone was just as informative for forecasting the future level of infection in the community as when TF, TI and PCR data were combined." (PMID 26652272, 2015). "At 3 h post infection, transferrin-positive recycling endosomes were accumulated in ERC at a juxta-nuclear region, possibly near the centrosome (white arrowheads)." (PMID 26575487, 2015). "TF expression by monocytes or microvesicles in the circulation is minimal under normal physiologic conditions, while circulating monocytes perturbed by infection or inflammation upregulate TF, and subsequently, release TF via microvesicles." (PMID 26085816, 2015). "During infection in host animals, bacterial organisms are obligated to compete with host iron-chelating substances, such as transferrin and lactoferrin, to acquire ferric ions." (PMID 25712807, 2015). "Infection was detected using the Amplicor CT/NG assay and TF was identified by clinical examination using the World Health Organization (WHO) simplified grading system." (PMID 24722392, 2014). "Transferrin is likely involved in immunomodulation after mycotic infection to create an unfavorable environment in the hemolymph for fungal invasion because the removal of iron is very important for pathogens." (PMID 25379782, 2014).
infection (continued). "In this setting, we can model the change in the relationship between infection and disease, and it seems to hold even when TF prevalence drops below 10%, with the odds of infection in children with TF reduced by about 26% with each round of MDA." (PMID 24722392, 2014). "Among children aged 0–1 year with TF, the odds of infection were unchanged with each MDA (OR 0.93, 95% CI 0.77 to 1.12, p = 0.425)." (PMID 24722392, 2014). "Transferrin acts as an antimycotic mediator, preventing oxidative stress and enhancing survival against infections." (PMID 25379782, 2014). "An elevated level of transferrin was also observed at infection for all the semi-immune mice strains when compared with the uninfected mice." (PMID 23978045, 2013). "Transferrin is known to regulate iron metabolism and also an indicator of inflammatory response during infection." (PMID 23978045, 2013). "In line with previous findings intraperitoneal injection of human transferrin prior to infection increased bacterial loads at 6 h and therefore all experiments presented were performed with the addition of human transferrin." (PMID 23359320, 2013). "Because iron is so essential for the in vivo proliferation of bacterial pathogens, its limitation by transferrin and lactoferrin is a key innate immune defence against infection." (PMID 24381789, 2013). "We sampled Ct infection and determined TF prevalence in children aged 0–5 years, as this group is most likely to harbour infection." (PMID 23785525, 2013). "The prevalence of Ct infection was 0.8% in children aged 0–5 years at baseline, and it appeared sporadically distributed in a manner unrelated to TF in individuals, or TF prevalence in EAs or districts." (PMID 23785525, 2013). "The percentage of transferrin saturation was also decreased in infected mice, becoming significantly reduced (p<0.05) by 9 months post-infection compared to control mice." (PMID 23185574, 2012). "An enrichment of gene transcripts encoding the iron binding proteins transferrin and ferritin was detected in the data obtained from the A. aegypti transcriptome analysis in response to wMel and wMelPop-CLA infections." (PMID 22383881, 2012). "To confirm that depletion of iron pool in host by LD was actually the cause of decreased PHD activity, we supplemented physiological concentration of holo-transferrin or apo-transferrin after LD infection and determined PHD activity." (PMID 22701652, 2012). "At 6 months post-infection, serum iron concentrations were significantly lower due to H. felis infection and by 9 months post-infection, the transferrin saturation was also markedly lower in the infected cohort." (PMID 23185574, 2012). "The highest biological effects of the experimental infection are observed at 6 h post infection and were significantly more pronounced in congenic transgenic mice expressing human transferrin." (PMID 21811575, 2011). "Infection with the complemented ΔcagA (CagA*) resulted in restoration of the phenotype of increased transferrin transcytosis." (PMID 21589900, 2011). "To determine if the transferrin recycling pathway is involved in Hp colonization of the cell surface, we silenced transferrin receptor expression during infection." (PMID 21589900, 2011). "Transferrin and its receptor (TfR1) play an important role during infection of macrophages with bacterial pathogens that prefer an intracellular lifestyle." (PMID 20184753, 2010). "During different stages of colonization and infection available iron sources differ, particularly the host iron-binding proteins haemoglobin, transferrin, and lactoferrin." (PMID 19352437, 2009). "Our results show that C3H/HeJ mice have higher levels of serum hepcidin and ferritin than C3H/HeSnJ mice and that both strains have low transferrin saturation values 21 days after infection." (PMID 19930711, 2009). "Transferrin levels increased in all strains after infection and stayed relatively constant from day 3 (BALB/c) or day 9 (A/J and C57BL/6)." (PMID 19365556, 2009).